FLT1 (fms related receptor tyrosine kinase 1)
Diseases named in the same sentence as FLT1 in open-access papers (continued):
Sharing a sentence is not in itself a finding about the gene and the disease.
tumor (continued). "Vascular endothelial growth factor-A expression is elevated in tumours in response to a variety of stimuli, and its activity is largely restricted to vascular endothelial cells via two high-affinity receptors, Flt-1 (VEGF-R1) and KDR/Flk-1 (VEGF-R2)." (PMID 14612898, 2003). "We, therefore, hypothesize that PARPi treatment leads to increased PGF expression in tumors, which in turn facilitates pro-survival signaling in FLT1-proficient (but not FLT1-deficient) tumor cells and culminates in the development of PARPi resistance." (PMID 38956205, 2024). "However, one point of distinction between our current study and the published literature is that Flt1-proficient and -deficient tumor cells show only modest growth differences in the absence of PARPi treatment in our tumor models." (PMID 38956205, 2024). "Furthermore, FLT1 was also found to be a potential tumor suppressor, and the hypermethylation of FLT1 may contribute to polycyclic aromatic hydrocarbon-induced carcinogenicity." (PMID 35222371, 2022). "Genes such as Cacna1e and FLT1 were also significantly upregulated under cancerous conditions, and evidence suggests that these genes could be crucial factors for the macrophage M2 phenotype in the tumor microenvironment." (PMID 34987497, 2021). "In contrast to the expression of both Flk-1 and Flt-1 in endothelial cells, Flt-1 is widely expressed in many non-endothelial cell types, including hepatocytes, bone marrow progenitor cells, monocytes, macrophages, neural cells, vascular smooth muscle cells, and various tumor cells." (PMID 23799978, 2013). "Notably, targeted reduction of FLT1 activity can inhibit tumor cell growth." (PMID 20422012, 2010). "FLT1 is also a receptor for placental growth factor (PGF), which positively regulates cell proliferation and tumor growth." (PMID 41020821, 2025). "Co‐occurring alterations with KRAS included FLT1 (28%, 9/32, p = 0.033), APC (16%, 5/32, p = 0.015), and KEAP1 (16%, 5/32), with four of these tumours also harbouring STK11 alterations, forming a KRAS‐KEAP1‐STK11 mutational profile (13%, 4/32)." (PMID 41015991, 2025). "Bevacizumab inhibits the binding of VEGF to its receptors, FLT-1 and KDR, on the surface of endothelial cells, resulting in the reduction of tumor vascularization and a subsequent reduction in tumor growth." (PMID 39003252, 2024). "Consequently, FLT1 may represent a promising novel target for these anti-tumor drugs." (PMID 38576019, 2024). "FLT1 positivity was observed in 73.3% of RCC cases, it appeared as cytoplasmic with occasional nuclear brown staining in endothelial and the tumor cells." (PMID 39687450, 2024). "FLT1 and KDR are receptors of VEGF, which is the most important factor in promoting angiogenesis in tumours." (PMID 37313656, 2023). "VEGF‐A and its receptors VEGFR‐1 (Flt‐1) and VEGFR‐2 (KDR/Flk‐1) play major roles in physiological as well as pathological tumor angiogenesis." (PMID 37803932, 2023). "RNAseq analysis of tumour tissue also confirmed the effect that ETC-159 had on OS intratumoral angiogenesis, downregulating expression of angiogenic signalling intermediate FLT1." (PMID 36902186, 2023). "We found significantly positive Pearson R values for the majority of tumor entities, especially regarding correlations between FAP and the angiogenesis-related genes FLT1, KDR, HIF1A, and ETS1." (PMID 36672341, 2023). "Combined with the immunohistochemical data from the database, we investigated the protein level changes of CAV2, FLT1, THBS3 and VAV3 in tumor samples and normal control samples." (PMID 36950136, 2023). "Among the identified hub genes, we found that only C1GALT1 was significantly overexpressed in the tumor cells, whereas LEP4, ERG, and FLT1 were primarily expressed in the endothelial cells in scRNA-seq dataset." (PMID 37735483, 2023).
tumor (continued). "In CSCC samples, we found an apparent co-localization of VEGF-A, KDR, and Flt-1 in neoplastic keratinocytes of CSCC, suggesting an autocrine positive regulation to promote tumor growth and invasion, as has been postulated before for oral SCC." (PMID 35878392, 2022). "VEGF-A interacts with higher infinity with Flt-1, although KDR induced stronger phosphorylation signaling cascade to induce proliferation, survival, and increase permeability in endothelial or tumor cells." (PMID 35878392, 2022). "According to our analysis, the A to G substitution (rs7326277) generates the miR-193a-5p binding site in the 3′UTR of the VEGFR1 (FLT1) gene, an important player in tumor progression, inflammation, and epithelial–mesenchymal transition." (PMID 36430200, 2022). "Receptors for VEGF (VEGFR) are expressed on both tumor endothelium and tumor cells and VEGFs act through three different VEGF receptors VEGFR1 (Flt1), VEGFR2 (Flk 1) and VEGFR3 (Flt4)." (PMID 36291938, 2022). "However, extensive mutational analysis of tumor genes could not identify predictive markers of regorafenib efficacy, including among genes involving in angiogenesis (FLT1, FLT2, FLT3, FLT4, KDR, TEK (TIE2), and VHL)." (PMID 33322802, 2020). "Recent studies have demonstrated that in addition to homing to the primary tumor, a distinct subset of HSPCs that express vascular endothelial growth factor receptor 1 (VEGFR1; also known as Flt1) can home to tumor-specific pre-metastatic sites." (PMID 32582203, 2020). "Bevacizumab inhibits VEGF to bind its receptor flt-1 and KDR on endothelial cells to reduce tumor angiogenesis and tumor growth by inactivating VEGF." (PMID 31598150, 2019). "Based on logFC and Betweenness Centrality index values for network nodes, tumor VM formation-related genes, namely, KDR, FLT1, and CDH5, were revealed to be important upregulated hub genes." (PMID 30674871, 2019). "We found ten potential prognostic genes, including eight tumor suppressor and/or driver genes (VEGFA, CCND1, BAX, IL7R, SHC1, FLT1, IL7, and JAK3), as well as two chemokines (CXCL9 and CXCL10)." (PMID 31661791, 2019). "Recent studies have shown that FLT1 present and functional in different human cancer cells, and VEGF activation of FLT1 can be involved in the process of tumor progression." (PMID 31289124, 2019). "The VEGFR family includes VEGFR-1(Flt-1), VEGFR-2(KDR/Flk-1), VEGFR-3(Flt-4), NRP-1 and NRP-2 with VEGFR-2 is supposed to be closer to generation of tumor vessels." (PMID 29662638, 2018). "In order to analyze the potential of detachment, migration and metastasis of Flt-1+ cells vs Flt-1- cells, we examined the presence of RFP+ tumor cells in mouse blood 8 weeks after subcutaneous tumor cell transplantation by flow cytometry." (PMID 29100318, 2017). "Flt-1 is a vascular endothelial growth factor (VEGF) receptor: these growth factors are secreted in order to induce capillary growth, thus providing the tumour with a vasculature blood supply." (PMID 28946666, 2017). "Using both in vitro and in vivo gold standards for identification of CSCs, including tumor sphere formation, chemo-resistance and tumor formation in serial adoptive transplantation, we were able to show that the CSCs may be predominantly present in the Flt-1+ fraction." (PMID 29100318, 2017). "Of these, KDR and FLT1 are both receptors for VEGFA, the predominant mediator of angiogenesis in tumor progression." (PMID 28388297, 2017). "Binding of bevacizumab prevents the interaction of VEGF with its receptors VEGFR-1 (Flt-1) and VEGFR-2 (KDR), and disrupts the formation of new tumor vasculature." (PMID 28134851, 2017). "Therefore, decreased Flt1 expression in the RJ423200c cells may suppress proliferation and reduced Vegfc expression in RJ423200c cells could restrict angiogenesis, both of which could contribute to the observed reduction in tumor growth." (PMID 28423599, 2017).
tumor (continued). "Tumor angiogenesis can be blocked by the miR-200 family members via targeting the VEGF signaling pathway components, such as VEGF-A, FLT1/VEGFR1, and KDR/VEGFR2." (PMID 27240340, 2016). "The primary tumour induces the production of MMP-9 in endothelial cells and macrophages in the lungs via a mechanism dependant on VEGFR-1/FLT-1 tyrosine kinase (TK) that promote metastasis." (PMID 26913068, 2016). "Angiogenesis is a key factor for tumor growth and involves VEGF and the activation of VEGF receptors, Flt1 and KDR." (PMID 26174150, 2015). "As determined by the RNA-seq analysis, the overall expression of FLT-1 or sFLT-1 was similar in the CD33+ IMMCs from tumors and adjacent lung tissue, however the mFLT-1 was specifically upregulated in tumor IMMCs." (PMID 26046767, 2015). "DTCs were detected using immunocytochemistry, the level of tumor hypoxia using NMR spectroscopy, CD68, CD34, VEGF, and VEGFR-1 (Flt-1) expression using immunohistochemistry, and MMP-2 and MMP-9 activity using zymography." (PMID 24669218, 2014). "In total, 3.5% of the transcriptome is regulated by PARP-1 with 60–70% positively regulated, including genes involved in tumor promotion such as JUND, MDM2, HGF, FLT1 (VEGFR1), EGFR, HIF2A (EPAS1), SPP1 (OPN), MMP28, ANGPT2, and PDGF." (PMID 24350055, 2013). "In the majority of cases, tumour cells of DCIS showed expression of Flt-4, bFGF-R1, VEGF-C, and ETAR, whereas Flt-1 and bFGF expression was rarely observed." (PMID 15841074, 2005). "In addition, cluster 25 relates to the regulation of VEGF-induced migration, including the expression of key VEGF-related genes (NRP1, NRP2, FLT1, KDR, PGF), which can promote tumour dissemination by supporting the invasion of malignant cells into the stroma." (PMID 38331751, 2024). "An analysis of tumor growth and weight at endpoint revealed that Flt1 repression in tumor cells re-sensitizes PARPi-resistant tumors to talazoparib (EV3I), which can be rescued by FLT1 re-expression (EV3K,L)." (PMID 38956205, 2024). "First, FLT1 blockade interrupts pro-survival PGF-FLT1-AKT signaling in tumor cells, and second, it increases T-cell infiltration and the immune response, possibly by altering the tumor-cell secretome and chemokine milieu." (PMID 38956205, 2024). "Moreover, while FLT1 blockade with PARPi treatment is accompanied by increased CD8+ T-cell infiltration and tumor regression in immunocompetent mice, these effects were absent in T-cell-deficient nude-Foxn1nu mice." (PMID 38956205, 2024). "Besides, the expression of 7 genes (EZH2, FLT1, IRS1, KDR2, MYB2, JUN, and TIMP2) was significantly different in metastatic tissue when compared with the primary tumor." (PMID 36879084, 2023). "We also observed that MDSC-secreted VEGFA and multiple chemokines CCL2, CXCL1, CXCL2, CXCL3, and CXCL8 could act on endothelial cells via VEGFA-KDR/FLT1 and CCL2/CXCLs-ACKR1 interactions, which were crucial for tumor angiogenesis." (PMID 37475874, 2023). "Based on marker genes for every cluster, we revealed one set of lymphatic endothelial cells (cluster 9, TFF3 +) and nine sets of vascular endothelial cells (FLT1 +): One was mostly interface-derived (clusters 2; HLA-DQA2 +) and three were mostly tumor-derived (clusters 4, 6 and 8; ROBO1 +)." (PMID 37644609, 2023). "Furthermore, differential analysis showed vascular-related genes FLT1, TMB, neoantigen, PD-L1 protein (CD274), Tumor Immune Dysfunction and Exclusion (TIDE), and T cell exclusion score were significantly different between the high- and low-risk groups." (PMID 37189138, 2023). "The vascular endothelial growth factor (VEGF) family, including VEGF; placental growth factor (PLGF); and their receptors Flt-1, sFlt-1, and KDR (also known as VEGFR-1, sVEGFR-1, and VEGFR-2, respectively), are the most important promoters of physiological and tumor angiogenesis." (PMID 35878392, 2022).
tumor (continued). "VEGF-A and PIGF, which are major pro-angiogenic factors associated with cancer angiogenesis and are pro-tumorigenic and Flt-1, also known as vascular endothelial growth factor receptor 1 (VEGFR-1), is a high-affinity tyrosine kinase receptor for VEGF involved in tumor growth and metastasis." (PMID 35154142, 2022). "The present study examined mRNA and protein expression of VEGF-A, PLGF, and their receptors KDR and Flt-1 in feline CSCC and NHS controls, testing the prediction that these mediators of tumor angiogenesis would be elevated in cutaneous carcinoma relative to normal skin." (PMID 35878392, 2022). "In addition, endothelial growth factor receptor 1 (VEGFR-1/Flt-1) and receptor 3 (VEGFR-3) are highly expressed on various tumor vascular endothelial cells." (PMID 33995663, 2021). "Nuclear import of HIF-1A as a transcription factor is a hallmark event in HIF-1 dependant hundreds of target gene activation, such as angiogenic gene including VEGF-A, Flt-1, ang-1, MMP-2 and MMP-9 which promotes tumour angiogenesis, metastasis and clinical prognosis." (PMID 33403040, 2021). "Tumor hypoxia represents a potent stimulus for continued induction of several key angiogenic cytokines, including the vascular endothelial growth factor (VEGF) and its endothelial-specific receptors VEGFR1 (Flt1) and VEGFR2 (KDR/Flk1)." (PMID 33999935, 2021). "According to the marker genes, these clusters were designated as blood endothelial cells (FLT1; clusters 0–3, 5, 6), lymphatic endothelial cells (PDPN: cluster 4), tumor endothelial cells (HSPG2: clusters 0 and 2–6), and normal endothelial cells (MT2A; clusters 0–6)." (PMID 33083004, 2020). "Since sFLT1 protein expression was induced by 5azadC treatment in three choriocarcinoma cell lines, we investigated the DNA methylation pattern of the FLT1 promoter region in cytotrophoblasts, HTR-8/SVneo cells, HEK293 cells, choriocarcinoma cells, and a tumor specimen." (PMID 32041578, 2020). "In details, the decrease of FGF2, FLT1, CCL2 mRNA, along with increase of SERPINF1 mRNA were observed in EP300 knockdown ESCC cells, predicting that EP300 may promote tumor initiation via angiogenesis in ESCC." (PMID 31632486, 2019). "When specifically binding to VEGF, it prevents VEGF from interacting with VEGF receptors on the surface of endothelial cells (Flt-1 and KDR) and blocks the VEGF-mediated pathway, which leads to suppression of vascular endothelial cell proliferation and tumor angiogenesis." (PMID 31684985, 2019). "Two years later, the same authors put forward that sv-cystatin was also able to suppress tumor angiogenesis by reducing the level of vascular endothelial growth factor (VEGF)-A165, basic fibroblast growth factor (bFGF), and fms-related tyrosine kinase 1 (Flt-1)." (PMID 30501116, 2018). "In the current study, the expression of both VEGF receptors (VEGF-R), KDR and FLT1, on EVs was found to be similarly high in all patient sub-groups compared to HC and was not affected by tumor existence or exposure to chemotherapy." (PMID 28968987, 2017). "Although the expression of six endothelial differentiation marker genes (PECAM1, vWF, FLT1, FLT4, KDR, CDH5) was significantly lower in normal and tumor ADSC, there was significantly greater expression of PDGFRB in ADSC when compared to BEC and NORMA1 MEC cells." (PMID 26968831, 2016). "To obtain further insight into tumor vascularization and VEGFR expression by cancer and non-tumor cells, we used real-time qRT-PCR to quantify species-specific mRNAs of PECAM1/CD31, ENG/CD105, FLT1/VEGFR1, KDR/VEGFR2 and VEGFA genes in a large series of 150 xenografts from different tumor types." (PMID 24625025, 2014). "Interestingly, artesunate also inhibits tumor angiogenesis by downregulation of VEGF, KDR/flk-1, Flt-1, NF-κB, and MMPs." (PMID 24223058, 2013).
tumor (continued). "Flt-1 has also been investigated for its role in cancer where it acts as a positive regulator of the pathological angiogenesis seen with tumor formation, which opposes the physiological role of Flt-1 as a negative angiogenic regulator." (PMID 23618411, 2013). "The smallest of the VEGF isoforms, VEGF121 binds to two receptors designated VEGFR-1 (Flt-1/FLT-1) and VEGFR-2 (Flk-1/KDR), both of which are over-expressed on the endothelium of tumor vasculature but virtually undetectable in the vascular endothelium of adjacent normal tissues." (PMID 21849059, 2011). "The findings of nuclear FLT1 protein and expression of corresponding ligands in MLS and normal tissues may have implications for tissue homeostasis and tumor development through auto- or intracrine signaling." (PMID 20515481, 2010). "Endogenous murine sFLT-1 protein could not be detected in untreated tumor-bearing nude mice, possibly due to poor recognition of murine sFLT-1 by the anti-human FLT-1 antibody 11G2, and/or to serum levels below the limit of ELISA detection." (PMID 36551660, 2022). "Lambrechts and co-workers classified tumor endothelial cells in different clusters based on the marker genes identified; Lymphatic endothelial cells (PDPN+, PROX1+), tumor-derived blood endothelial cells (FLT1+, IGFBP3+, and SPRY1+), malignant, and non-malignant endothelial cells." (PMID 33763348, 2021). "However, comparison of the tumor-adjacent gastric tissue between HP+ and HP- patients revealed 8 differentially methylated CpG sites located within 7 genes (CCNA1, CSPG2, DAB2IP, DIO3, FLT1, STAT5A and TWIST1)." (PMID 24674026, 2014). "Interestingly, these results were achieved using VEGFR1_MOe13 targeting the murine Flt-1 transcript, while treatment with a VEGFR1_MOe13 construct targeting human FLT-1 did not demonstrate tumor regression in vivo." (PMID 22438952, 2012). "The importance of FLT1, PGF, VEGFA and VEGFB expression and their functions in MLS/RCLS tumor development remain unclear but our results point out this receptor/ligand system as operational in MLS/RCLS and as such a potential target for intervention in this tumor type." (PMID 20515481, 2010). "Angiogenesis-related genes (FLT1, KDR, SPARC, INSR, ANGPT2, and FLT4) and MHC-I molecules (HLA-A, HLA-B, HLA-C, HLA-E, and HLA-F) were highly expressed in cluster 3 ECs, indicating that the cells may function as antigen-presenting cells and promote tumor parenchymal angiogenesis." (PMID 37533434, 2023). "However, FLT1 traditionally regulates angiogenesis through it's function in endothelial cells, not tumor cells, so it remains unclear how tumor cell Flt1 expression could influence tumor vascularity." (PMID 28423599, 2017). "Moreover, Flt-1+ CRC cells were more frequently detected in the circulation, suggesting that Flt-1+ CRC cells may be not only enriched for CSCs, but also enriched for a fraction of circulating tumor stem-like cells." (PMID 29100318, 2017). "Notably, FLT-1 expression in cells of the myeloid lineage has been shown to regulate VEGF/PLGF-oriented migration, survival, and production of angiogenic factors, which can promote tumor growth, suggesting that it may have a protumorigenic function in NSCLC." (PMID 26046767, 2015). "We found that CAV2 and VAV3 were significantly highly expressed in tumor samples, whereas the expression levels of THBS3 and FLT1 were not significantly altered in tumor samples." (PMID 36950136, 2023). "Although growth of primary tumor was not affected, normalization factors produced by of endothelial cells (EC), such as VEGF and Flt1 prevent tumor dissemination and metastasis." (PMID 33673417, 2021). "IBC tumor samples have higher mRNA expression of angiogenic factors, including VEGF, Flt-1, Ang1, Ang2, and Tie2, than do non-IBC tumor samples." (PMID 32883032, 2020).
tumor (continued). "Expression of full-length forms of the VEGF/PLGF receptors KDR and Flt-1 were reduced (p = 0.0254 and p = 0.0348, respectively) in CSCC relative to NHS, whereas expression of the alternatively spliced decoy receptor sFlt-1 was indistinguishable in tumor and control samples (p = 0.17)." (PMID 35878392, 2022).